HAS3 (hyaluronan synthase 3)
Description:
Catalyzes the addition of GlcNAc or GlcUA monosaccharides to the nascent hyaluronan polymer. Therefore, it is essential to hyaluronan synthesis a major component of most extracellular matrices that has a structural role in tissues architectures and regulates cell adhesion, migration and differentiation. This is one of three isoenzymes responsible for cellular hyaluronan synthesis.
Tractability: Antibody: UniProt places it where antibodies can reach, with high confidence; its Gene Ontology location is reachable by antibodies, with high confidence; UniProt predicts a signal peptide or a membrane-spanning region. PROTAC: ubiquitination databases record sites on it.
Safety:
Unwanted effects reported when the protein is acted on. In parentheses: how it was acted on, where the effect was seen, and who reports it.
cardiomyopathy risk (source: ClinPGx)
Gene: Protein-coding gene on chromosome 16 (69,105,653 to 69,118,719, forward strand). Ensembl gene ENSG00000103044.
Subcellular location: Cell membrane; Golgi apparatus membrane; Golgi apparatus, trans-Golgi network membrane; Early endosome
Subcellular location (Human Protein Atlas): Microtubules
Pathways (Reactome):
Metabolism: Hyaluronan metabolism
Gene Ontology:
Molecular function: hyaluronan synthase activity; identical protein binding; protein binding
Biological process: hyaluronan biosynthetic process; positive regulation of DNA-templated transcription; positive regulation of hyaluranon cable assembly; carbohydrate metabolic process; extracellular matrix assembly; polysaccharide biosynthetic process
Cellular component: early endosome; Golgi apparatus; Golgi membrane; hyaluranon cable; plasma membrane; UDP-N-acetylglucosamine transferase complex; membrane; cytoplasm; nucleus
Genetic constraint (gnomAD): Loss-of-function variants: 27 observed, 47.69 expected, observed/expected ratio (o/e) 0.57, 90% interval 0.42 to 0.78. The upper end of that interval is the gene's LOEUF score, 0.78, which puts it in group 3 of 6, group 1 being the genes least tolerant of losing a copy. Missense variants: 504 observed, 744.86 expected, observed/expected ratio (o/e) 0.68, 90% interval 0.63 to 0.73. Synonymous variants: 331 observed, 311.17 expected, observed/expected ratio (o/e) 1.06, 90% interval 0.97 to 1.16.
Homologues: Orthologues: chimpanzee HAS3 (100% identical), dog HAS3 (99% identical), pig HAS3 (98% identical), rabbit HAS3 (98% identical), rat Tango6 (98% identical), guinea pig HAS3 (97% identical), mouse Has3 (97% identical), macaque HAS3 (87% identical), tropical clawed frog has3 (79% identical), zebrafish has3 (76% identical). Paralogues in human: HAS2 (69% identical), HAS1 (56% identical).
Diseases named in the same sentence as HAS3 in open-access papers:
HAS3 is named in the same sentence as 95 diseases in open-access papers, as found by Europe PMC text mining. Sharing a sentence is not in itself a finding about the gene and the disease. The quoted sentences say what the papers report.
breast carcinoma (15 papers, 2013 to 2025). "The results showed that overexpression of HAS3 in human breast cancer cells inhibits cell proliferation through cell cycle arrest at the G2/M phase." (PMID 34770956, 2021). "This has been shown in human chondrosarcoma, HAS3 overexpressing MCF7 breast cancer, melanoma cells, and HAS3 overexpressing MCF10A cells." (PMID 34533887, 2021). "We also demonstrated the mechanisms of HAS3-induced G2/M cell growth cycle arrest accompanied by autophagic cell death in breast cancer cells." (PMID 34770956, 2021). "The results of IHC experiments in breast cancer tissue sections also revealed that HAS3 protein expression was significantly higher in normal tissue (green rectangle) than in tumor tissue (red rectangle)." (PMID 34770956, 2021). "In this study, we detected the hyperacetylation of α-tubulin in human breast cancer cells (MDA-MB-231) by treating a culture medium containing HA or the forced expression of HAS3 by plasmid transfection." (PMID 34770956, 2021). "Decreased HA levels in subcutaneous Has3-KO mouse tissues promoted orthotopic breast cancer (E0771) cell-derived allograft tumor growth." (PMID 34770956, 2021). "In conclusion, the HAS3 and its enzyme products were detected in the stroma breast tissues at a high level, attenuating effects for induced breast cancer cell death and inhibiting the cancer cells invasion at the initial stage." (PMID 34770956, 2021). "In conclusion, HAS3 and HA were detected in the stroma breast tissues at a high level attenuates effects for induced breast cancer cell death, and inhibit the cancer cells invasion at the initial stage." (PMID 34770956, 2021). "Next, we analyzed the correlation of compression-upregulated metabolic genes with compressive stress markers (COL1A1, COL3A1, HAS2, and HAS3 genes) and tumor size in breast cancer subtypes: luminal A (LumA), luminal B (LumB), Her2, and triple-negative (TN)." (PMID 31428701, 2019). "4-MU also inhibits HA synthesis via repression of HAS2 and/or HAS3 mRNA in breast cancer, melanoma and ovarian cancer cells." (PMID 23426189, 2013). "Among the compression-upregulated metabolic genes, the expression of ENO2 gene was significantly and positively correlated with COL3A1 and HAS1 genes, whereas PFKFB3 genes were significantly and positively correlated with that of COL1A1, HAS2, and HAS3 genes in breast cancer patient tissues." (PMID 31428701, 2019). "In contrast to our qPCR results, it was reported for breast cancer that HAS2 knockdown in Hs578T cancer cells leads to an upregulation of HAS1, HAS3 and HYAL1." (PMID 35767191, 2022). "The breast cancer cell lines Hs578T and MDA-MB-231 (parental line and a bone-seeking clone) expressed high levels of HAS2 and lower mRNA levels of HAS1 and HAS3." (PMID 36497283, 2022). "Gene set analysis revealed that in human breast cancer cell lines the expression of these seven genes (MUC1, PLAU, FABP7, SPARC, HAS2, HAS3, SOX4) are higher in basal-B subtype compared to other subtypes." (PMID 29435170, 2018). "Interestingly, we found that the HAS3 protein was seen at a higher level in normal breast epithelial cells (MCF-10A, MCF-12A, and 184A1) when compared to the breast cancer cell lines." (PMID 34770956, 2021). "However, a negative correlation with HAS3 in breast cancer could be an interesting marker to continue the study." (PMID 32610620, 2020). "Non-aggressive breast cancer cells express high levels of HAS3 and lower levels of HAS2 compared with aggressive breast cancer cells." (PMID 33986244, 2021). "Our results show a positive correlation between BRCA1 and CD44, HAS2, HAS3 and HYAL1 in colorectal but not breast cancer." (PMID 32610620, 2020). "Aggressive ovarian and breast cancer cells express high levels of HA synthase 2 (HAS2) and lower levels of HA synthase 3 (HAS3) compared to non-aggressive cancer cells." (PMID 25852691, 2015).
ovarian carcinoma (11 papers, 2009 to 2022). A malignant neoplasm originating from the surface ovarian epithelium. "However, elevated HAS3 protein levels have also been associated with ovarian cancer, and overexpression of HAS3 promotes tumor growth in a preclinical model." (PMID 25147816, 2014). "This is therapeutically significant, as increased HAS2 and HAS3 expression was observed in chemotherapy-resistant ovarian cancer cells." (PMID 35767191, 2022). "The expression of the HA synthases HAS2 and HAS3 was significantly increased in chemoresistant compared to chemosensitive primary ovarian cancer cells isolated from patient ascites." (PMID 31443261, 2019). "In this study we found that the expression of the HA synthases HAS2 and HAS3 was significantly increased in chemoresistant compared to chemosensitive primary ovarian cancer cells isolated from patient ascites." (PMID 31443261, 2019). "Previous studies have shown 4-MU treatment inhibits HA production and spheroid formation by HAC-2 ovarian clear cell carcinoma cells and HAS3 expression by SKOV3 ovarian cancer cells." (PMID 31443261, 2019). "CBP treatment increased the secretion of HA in ovarian cancer cell lines by increasing HA synthesis, as we found corresponding increased Has2 and Has3 expression in OVCAR-5 and increased Has3 expression in OV-90 and OVCAR-3 cells." (PMID 24124770, 2013). "Immunohistochemical stainings confirmed that the levels of HAS1 and HAS3 were relatively low in ovarian cancers, while the signal for HAS2 was more widespread, in line with the real-time RT-PCR-analysis." (PMID 19435493, 2009). "Treatment with carboplatin significantly increases expression of HAS2 and HAS3, and the resultant increase of HA secretion may contribute to chemoresistance in ovarian cancer." (PMID 29849953, 2018). "The first research about effects of 4-MU on ovarian cancers revealed that 4-MU suppressed synthesis of hyaluronic acid in SKOV-3 human epithelial ovarian cancer cell lines via downregulation of UDP-glucuronic acids and HAS3 expressions." (PMID 32645961, 2020). "Carboplatin significantly increased expression of HAS2, HAS3 and ABCC2 and HA secretion in ovarian cancer cell conditioned media." (PMID 24124770, 2013). "In summary, HAS3 did not appear to play a central role in the survival of ovarian cancer patients in our study." (PMID 35767191, 2022). "It is likely that the tumour inhibitory effects of 4-MU in vivo may be mediated by inhibiting HA in the tumour microenvironment as HRA ovarian cancer cells expressed low levels of HAS2 and HAS3." (PMID 31443261, 2019). "In ovarian cancer patients, high HAS1 levels in ovarian cancer cells but not HAS2 or HAS3 are associated with reduced overall survival." (PMID 21541039, 2011).
melanoma (10 papers, 2015 to 2025). A malignant, usually aggressive tumor composed of atypical, neoplastic melanocytes. "The high levels of IHH in HAS3-EVs were surprising, given that most of the reported studies on melanoma and other cancers have largely implicated the role of SHH in the process." (PMID 31820036, 2020). "We have also shown that HA synthesis in melanoma cells is associated with the release of HAS3 and IHH in EVs and there is a positive feedback regulation between HA and HH pathways." (PMID 31820036, 2020). "Coordinate expression of Id1 or Id3 or CD44 with HAS2 or HAS3 or CD44 was found to be associated with reduced survival of human melanoma patients." (PMID 30297743, 2018). "In melanoma, HAS3 overexpression induced EV shedding, and EVs isolated specifically from the cells overexpressing HAS3 were shown to trigger the Indian Hedgehog (IHH)-mediated upregulation of c-Myc in target cells, leading to the transformation of those cells." (PMID 39851567, 2025). "The protein expression of HAS2 and HAS3 was minimal in either control melanoma cells or melanocytes, but it dramatically increased in the presence of PACAP in all cases." (PMID 41465475, 2025). "As shown in our study, one of the mitogens from hedgehog signaling pathway, IHH, is significantly enriched in melanoma derived HAS3-EVs." (PMID 31820036, 2020). "However, it has been determined that sugars attached to UDP (UDP-sugars) influence the carrying of HAS3 to the plasma membrane of melanoma cells, thereby affecting the function of that enzyme and finally, HA synthesis." (PMID 33572239, 2021). "Similarly, forced expression of HAS3 promoted the tumorigenic ability of melanoma cells by accelerating tumor angiogenesis, but suppression of HAS2 or HAS3 inhibited the initiation and progression of primary and secondary tumor formation in vivo." (PMID 26322272, 2015). "Therefore, changes in the relative expression or activation of HAS2 versus HAS3 could critically influence HA size distribution and in turn, modulate melanoma cell behaviour, including adhesion, motility, and interactions with the tumour microenvironment." (PMID 41465475, 2025). "Using correlative light and electron microscopy imaging to detect HA, HAS3, and CD44, melanoma-derived EVs of various sizes were visualized while attached to the surface of normal human keratinocytes and breast cancer cells in vitro." (PMID 39851567, 2025). "Upon PACAP action, a strong immune signal was shown in melanoma cells and HAS2 signals were more pronounced than HAS3 signals." (PMID 41465475, 2025). "Since increased cell proliferation is one of the earlier traits in cancer progression, we analyzed the effect of MV3- and HAS3-EVs on the proliferation rate of HaCaT and WM115, a primary melanoma cell line." (PMID 31820036, 2020). "In this study, we demonstrated that EVs released from HAS3 overexpressing metastatic melanoma cells (MV3) interacted with keratinocyte (HaCaT) and melanoma (WM115) cells and induced proliferation and expression of EMT markers, similar to that in tumorigenesis." (PMID 31820036, 2020). "The tumor-promoting properties of these transcriptional regulators, and the ability of the HA/CD44 axis to promote their expression in response to BMP stimulation, likely underlies the association between coordinate expression of Id1/Id3 and HAS2/HAS3/CD44, and reduced survival of melanoma patients." (PMID 30297743, 2018). "Moreover, our unpublished in vitro observations support the idea that hyaluronan overexpression tends to restrict melanoma cell growth, and melanoma cell lines (MV3 and C8161) overexpressing HAS3 show reduced cell motility and proliferation." (PMID 27184066, 2016). "For example, our unpublished in vitro observations indicate that cell adhesion is reduced in melanoma cells overexpressing HAS3 and this ability are not reversed with eradication of hyaluronan." (PMID 27184066, 2016).
melanoma (continued). "(2020) published a study where they reported that HAS3-induced hyaluronan coated extracellular vesicles (EV’s) from melanoma cells induced EMT changes and increased proliferation of target cells, keratinocytes, similarly as CAF -derived hyaluronan has shown to promote melanoma cell proliferation." (PMID 35127523, 2021).
atopic dermatitis (7 papers, 2020 to 2025). "Overexpression of HAS3 in a model mimicking atopic dermatitis causes massive accumulation of HA in the intercellular spaces between keratinocytes of the living epidermal layers." (PMID 34831319, 2021). "Although HAS3 is one of the targets identified in downregulated miR-26a-5p, it is a direct target of upregulated miR-10a-5p in atopic dermatitis." (PMID 32806619, 2020). "Moreover, histamine increased histamine 1 receptor (H1R; 3.6 ± 0.7-fold, p < 0.01) and hyaluronic acid synthase 3 (HAS3; 3.6 ± 0.8-fold, p < 0.01) expression under atopic dermatitis conditions compared to healthy controls." (PMID 36615633, 2023). "In addition, the heparin-binding EGF-like growth factor (HB-EGF) released from keratinocytes in atopic dermatitis also increases HAS3 expression." (PMID 34831319, 2021). "Hyaluronan synthase subtypes HAS1 and HAS3 in RAAS exhibited distinct roles in skin biology, where HAS1 was associated with regular differentiation and repair processes, while HAS3 was linked to inflammatory responses, particularly in disorders like atopic dermatitis." (PMID 38612783, 2024). "HAS3 mRNA expression was significantly (p < 0.05) and H1R mRNA expression tended to be elevated after histamine stimulation under atopic dermatitis conditions compared to TH2 cytokine stimulation without histamine." (PMID 36615633, 2023). "HAS3 mRNA expression was found to be upregulated in lesional skin biopsies from atopic dermatitis patients compared to healthy or non-lesional skin, which may be seen as an indication of alterations in epidermal matrix metabolism in atopic dermatitis lesional skin." (PMID 36615633, 2023).
colon carcinoma (6 papers, 2014 to 2024). "Previously it was shown that dual FAK and HAS3 inhibition caused synergistic inhibition of colon cancer cell viability." (PMID 25277206, 2014). "In a study from 2003, it was found that HAS3 is overexpressed in metastatic tissue of colon carcinoma." (PMID 35767191, 2022). "Furthermore HAS3 knockdown showed inhibition in the growth of both colon cancer and oesophageal squamous cell carcinoma cell lines." (PMID 35767191, 2022). "For example, HAS3 expression in colon cancer cell line SW620 was required for matrix retention." (PMID 31762938, 2019). "Moreover, HAS3 is involved in the synthesis of the unbranched glycosaminoglycan hyaluronan, and it mediates tumor cell growth, invasion, and apoptosis in metastatic colon cancer cells." (PMID 39758846, 2024).